ASS1 (argininosuccinate synthase 1)
Diseases named in the same sentence as ASS1 in open-access papers (continued):
Sharing a sentence is not in itself a finding about the gene and the disease.
malignant pleural mesothelioma (7 papers, 2014 to 2025). A malignant neoplasm that arises from mesothelial cells in the pleura and shows a diffuse growth pattern. "The treatment of patients with ASS1-deficient malignant pleural mesothelioma with pegargiminase, an arginine deprivation therapy agent, has shown prolonged survival." (PMID 41300990, 2025). "In clinical settings, treatment with pegargiminase has been evaluated in patients with ASS1-deficient malignant pleural mesothelioma." (PMID 41300990, 2025). "Pegylated arginine deiminase (ADI-PEG20; pegargiminase) depletes arginine and improves survival outcomes for patients with argininosuccinate synthetase 1 (ASS1)-deficient malignant pleural mesothelioma (MPM)." (PMID 37010783, 2023). "In the treatment of ASS1‐deficient cutaneous melanoma, uveal melanoma, and malignant pleural mesothelioma, ADI‐PEG 20 was well tolerated and demonstrated antitumor activity." (PMID 34841717, 2022).
small cell lung carcinoma (7 papers, 2016 to 2025). Small cell lung cancer (SCLC) is a highly aggressive malignant neoplasm, accounting for 10-15% of lung cancer cases, characterized byrapid growth, and early metastasis. "In small cell lung cancer (SCLC), ADI-PEG 20 induced cell death in ASS1-deficient cells and inhibited tumor growth in ASS1-negative xenografts." (PMID 37445845, 2023). "Another study showed that approximately 45% of small cell lung cancers and 50% of cell lines assessed were negative for ASS1 and ASS1-deficient small cell lung cancers were sensitive to ADI-PEG20 (pegylated arginine deiminase)." (PMID 38053661, 2023).
acute myeloid leukemia (6 papers, 2021 to 2025). Acute myeloid leukemia (AML) is a group of neoplasms arising from precursor cells committed to the myeloid cell-line differentiation. "In the context of our research, inducing arginine deficiency through NEI-01 led to the death of ASS1-deficient acute myeloid leukemia (AML) cells by triggering sub-G1 cell cycle arrest and apoptosis." (PMID 39590860, 2024). "While the use of ADI-PEG 20 as a single agent in treating relapsed/refractory acute myeloid leukemia (R/R AML) showed unfavorable results (NCT01910012), even in patients with ASS1 deficiency, a combination therapy for high-risk AML with Venetoclax and Azacitidine is currently ongoing (NCT05001828)." (PMID 38539506, 2024). "In leukemia, the acute myeloid leukemia cells (AMLs) lack ASS1 expression, and deprivation of arginine by ADI-PEG20 reduces AML tumor burden in vivo and in vitro." (PMID 38053661, 2023). "Most patients with acute myeloid leukemia (AML) lack arginine succinate synthase-1 (ASS1), which leads to a decrease in arginine synthesis." (PMID 40129984, 2025). "In another study, it was found that human acute myeloid leukemia (AML) is highly dependent on Arg for survival, and therefore is Arg auxotrophic because of reduced expression of ASS1." (PMID 33477430, 2021).
colon carcinoma (6 papers, 2013 to 2024). "ASS1-deficient colon cancer cells had significantly lower survival following DNA damage than parental cells expressing ASS1." (PMID 38858597, 2024). "We now show that loss of ASS1 in colon cancer cells dysregulates nucleotide synthesis, enabling cell cycle progression despite DNA damage." (PMID 38858597, 2024). "Following Dox treatment or ASS1 loss, we found a significant reduction in total nucleotide levels in colon cancer cells." (PMID 38858597, 2024). "Consistent with the γH2AX foci levels, we observed longer comet tails representing more DNA damage in untreated and Dox-treated ASS1-KO colon cancer cells than in control cells." (PMID 38858597, 2024). "We found that DNA damage significantly reduced the levels of uracil to aspartate in colon cancer cells expressing ASS1." (PMID 38858597, 2024). "RNA analysis further confirmed that the upregulation in ASS1 expression following Dox is in colon cancer cells as well as in normal fibroblasts." (PMID 38858597, 2024). "By contrast, the expression of the same genes is downregulated in control ASS1-expressing Dox-treated colon cancer cells relative to untreated." (PMID 38858597, 2024). "Following Dox induction of DNA damage, ASS1-KO and parental colon cancer cells had a more significantly reduced accessibility over all promoters and, to a lesser degree, in enhancers." (PMID 38858597, 2024). "The upregulated expression of ASS1 has been found to support the proliferation of human colon cancer cells in vitro, as well as the migration and metastatic potential of human gastric cell lines, both in vitro and in mice with tumor xenografts." (PMID 30082427, 2018). "Upregulation of ASS1 enhances the ability of cells to recycle arginine and be less vulnerable to arginine deprivation, and inhibition of ASS1 has been shown to successfully impair the pathogenicity of colon cancer cells." (PMID 38383634, 2024). "To further decipher the role of ASS1 in the nucleus, we performed an anti-ASS1 immunoprecipitation–MS analysis of the nuclear fraction in HCT116 colon cancer cells." (PMID 38858597, 2024). "Like ASS1, the nuclear and cytosolic levels of ASL in colon cancer cells increased upon Dox-induced DNA damage." (PMID 38858597, 2024). "To investigate whether ASS1 provides a survival advantage following DNA damage, we measured survival after Dox treatment in colon cancer cells with and without ASS1." (PMID 38858597, 2024). "To investigate whether ASS1 is required to succinate SMARCC1, we first measured SMARCC1 levels in the chromatin-bound fraction following DNA damage in colon cancer cells without ASS1." (PMID 38858597, 2024). "To test this hypothesis, we analyzed the levels of uracil relative to aspartate in colon cancer cells with and without ASS1, following Dox treatment." (PMID 38858597, 2024). "Notably, in untreated colon cancer cells without ASS1, the G1 phase was prolonged significantly more than in cells expressing ASS1 and the G2 phase was shorter." (PMID 38858597, 2024). "Furthermore, we found that in HCT116 colon cancer cells treated with siIPO7, nuclear ASS1 levels did not significantly change following DNA damage compared to cancer cells treated with siControl." (PMID 38858597, 2024).
endometrial cancer (6 papers, 2017 to 2025). Primary or metastatic malignant neoplasm involving the endometrium (mucous membrane that lines the endometrial cavity). "In this study, we found a novel association between ASS1 and tumor cell properties of endometrial cancer." (PMID 28358054, 2017). "Notably, it was shown that ASS1-deficient endometrial cancer cells showed enhanced migration and invasion capability in response to increased arginine concentration due to suppressed DEPTOR expression." (PMID 28358054, 2017). "Based on their significantly lower levels of ASS1, American Indian endometrial cancer patients would be expected to benefit from these approaches to deplete arginine." (PMID 35887124, 2022). "In this study, ASS1 was found to be present at significantly higher levels in endometrial cancers from patients of American Indian race, compared to White ones (mean ± SD 142.31 ± 126.13 vs. 53.22 ± 76.60 relative units (RU), p = 0.005)." (PMID 35887124, 2022). "Before targeting PFAS or purine savage to improve Black endometrial cancer patient outcomes, the upregulation of ASS1 and the ultimate level of pyrimidine biosynthesis in endometrial cancer specimens would need to be determined." (PMID 35887124, 2022). "An endometrial cancer patient cohort was stratified into two different sub-groups with high and low expression of ASS1 (cutoff = FPKM 58.6; optimally selected)." (PMID 29731978, 2018). "First, we examined the expression levels of ASS1 in endometrial cancer cell lines by immunoblotting and immunocytochemistry." (PMID 28358054, 2017). "Taken together, these results show that ASS1 is a positive regulator of DEPTOR expression, and that the absence of ASS1 causes faster and higher mTORC1 activation, resulting in enhanced motility and invasion capability in endometrial cancer cells." (PMID 28358054, 2017). "Thus, in human endometrial cancer, tumor cells at the tumor invasive front, which had a low abundance of ASS1, showed lower DEPTOR expression and higher mTORC1 activation than those in the tumor center." (PMID 28358054, 2017). "In conclusion, we demonstrated that endometrial cancer cells with decreased ASS1 expression show increased cell motility and invasion capability in response to changes in arginine concentration and tend to invade toward stroma, ahead of other ASS1-expressing cells." (PMID 28358054, 2017). "To elucidate the mechanisms underlying the enhanced sensitivity to arginine in the absence of ASS1 expression in endometrial cancer cells, we performed DNA microarray-based gene expression profiling using EV and ASS1-KO HEC1B cells." (PMID 28358054, 2017). "To examine the significance of ASS1 in endometrial cancer cells, we disrupted the ASS1 gene in HEC1B and AN3CA cells, which showed ASS1 expression among the endometrial cancer cell lines, using the CRISPR/Cas9 system and successfully established ASS1-knockout (ASS1-KO) HEC1B and AN3CA cells." (PMID 28358054, 2017). "Moreover, we examined ASS1 and DEPTOR expression levels and their correlation among several endometrial cancer cell lines by immunoblotting." (PMID 28358054, 2017). "The low expression of argininosuccinate synthetase 1 (ASS1) leads to decreased expression of DEP domain-containing mTOR-interacting protein, an endogenous inhibitor of mTORC1 signal, and thus enhances the activity of the mTORC1 signaling, promoting invasion of endometrial cancer cells." (PMID 33401771, 2021).
leukemia (6 papers, 2017 to 2025). A malignant (clonal) hematologic disorder, involving hematopoietic stem cells and characterized by the presence of primitive or atypical myeloid or lymphoid cells in the bone marrow and the blood. "Analysis of the Microarray Innovations in Leukaemia (MILE) dataset uncovers reduced ASS1 levels in CML compared to most other leukaemia types." (PMID 37489735, 2023). "The transcriptomic expression of genes identified through proteomic analysis in the leukemia model indicated a generally uniform expression across all proteins, with notable overexpression observed for Ass1, which was exclusive to the DA1-3b/D365 dormant cells." (PMID 39223638, 2024).
lung adenocarcinoma (6 papers, 2021 to 2025). A carcinoma that arises from the lung and is characterized by the presence of malignant glandular epithelial cells. "Moreover, based on data from The Cancer Genome Atlas (TCGA), ASS1 loss confers significantly reduced 5‐year survival rates (25% “low” vs. 44% “high” ASS1 expression; p = 0.007; n = 500) for all stages of lung adenocarcinoma, including patients in adjuvant and metastatic treatment settings." (PMID 34382365, 2021). "Based on this premise, the potential role of argininosuccinate synthase 1 (ASS1), a key enzyme in arginine biosynthesis and which we identified as a predictor of sensitivity to HSP90 inhibitors in lung adenocarcinoma, warrants attention." (PMID 33802597, 2021). "In addition, proteins such as ASS1, ITCH, or UBE2L3 involved in pathways related to the inhibition of a particular molecular background could be used as potential response biomarkers, thereby improving the efficacy of this therapeutic approach to combat lung adenocarcinoma." (PMID 37762133, 2023).
non-small cell lung carcinoma (6 papers, 2021 to 2025). A group of at least three distinct histological types of lung cancer, including non-small cell squamous cell carcinoma, adenocarcinoma, and large cell carcinoma. "In the current study, we investigated the expression of ARG2 and ASS1 in non-small cell lung carcinomas." (PMID 34344457, 2021). "Increased levels of ASS1 have been observed in human non-small cell lung cancer (NSCLC) and colon carcinomas, which may be supporting arginine synthesis and facilitating cellular survival under low-nutrient stress conditions." (PMID 37601653, 2023).
liver cancer (5 papers, 2021 to 2025). An epithelial or non-epithelial malignant neoplasm that arises from the liver. "We discovered potential drugs for three proteins associated with liver cancer: ASS1 (arginine, aspartic acid, and citrulline), KRT8 (ambroxol, diltiazem, and amikacin), and STOML2 (chortetracycline, chlorzoxazone, and dirithromycin)." (PMID 39991825, 2025). "Moreover, urea cycle enzymes (ASS1 and CPS1) are inhibited in liver cancer, so the expression of them have decreased in liver cancer cells, and the increase of ASS1 and CPS1 caused by knocking down NFIB becomes insignificant." (PMID 35655758, 2022). "For external validation, we utilized liver cancer GWAS outcome data from a different cohort (ieu-b-4953) to validate the three MR proteins ASS1, KRT8, and STOML2, which presented the highest posterior probability in the colocalization analysis." (PMID 39991825, 2025). "In a single-cell liver cancer dataset, ASS1, KRT8, and STOML2 were expressed mainly in hepatic progenitor cells and malignant cells, with KRT8 predominantly found in hepatic progenitor cells and playing a role in the oncogenesis of malignant liver cells." (PMID 39991825, 2025). "Our results provide clear evidence that the low ASS1 expression level in HCC tissue negatively impacted the overall survival of patients with liver cancer." (PMID 33838671, 2021). "Because Korea ranks highest in the world in terms of liver cancer incidence and mortality rates, we also investigated the clinical value of ASS1 in Korean patients with HCC." (PMID 33838671, 2021). "We investigated ASS1 mRNA expression in tumor spheroids from primary HCC cells derived from eight Korean liver cancer patients." (PMID 33838671, 2021). "Here, we demonstrated the role of ASS1 as a tumor suppressor in liver cancer." (PMID 33838671, 2021). "We wondered whether a correlation existed between ASS1 expression in tumor tissue and survival rate after resection in patients with liver cancer." (PMID 33838671, 2021). "Moreover, we observed that low ASS1 expression in HCC tissue had a significant effect on the overall survival of patients with liver cancer." (PMID 33838671, 2021). "Specific knockout of liver NFIB leads to increased expression of ASS1 and CPS1, which promotes the occurrence of liver cancer by affecting the urea cycle." (PMID 35655758, 2022). "In contrast, some spheroids of Caucasian patient-derived liver cancer lines, such as Hep3B and PLC/PRF/5, exhibited ASS1 expression similar to that of normal hepatocytes." (PMID 33838671, 2021). "Additionally, feature plots and violin plots were generated for the tier 1 and tier 2 proteins ASS1, KRT8, and STOML2 and the liver cancer marker gene AFP." (PMID 39991825, 2025). "Therefore, the mechanism of ASS1 and CPS1 in liver cancer is still unclear, and further studies are needed." (PMID 35655758, 2022). "We also measured ASS1 mRNA expression in tumor spheroids from six Asian patient-derived HCC lines (SUN449, SUN475, SNU878, AMC-H1, AMC-H2, and Huh7), three Caucasian patient-derived liver cancer lines (Hep3B, Huh6, and adenocarcinoma line; SK-Hep1), and normal hepatocyte (Fa2N-4)." (PMID 33838671, 2021).
nasopharyngeal carcinoma (5 papers, 2017 to 2025). A carcinoma arising from the nasopharyngeal epithelium. "Notably, ASS1 deficiency has been associated with clinically aggressive states of nasopharyngeal carcinoma and pancreatic ductal adenocarcinoma." (PMID 34447409, 2021). "Argininosuccinate synthetase 1 (ASS1) plays an important role in the urea cycle by catalyzing the formation of argininosuccinate from arginine and fumarate and is a key enzyme in inhibiting the metabolism of nasopharyngeal carcinoma." (PMID 40821122, 2025).
viral infection (5 papers, 2019 to 2026). "ASS1, a key enzyme in arginine biosynthesis, has previously been implicated in viral infections such as HSV, where its depletion promotes viral replication." (PMID 40725077, 2025). "While ASS1′s role in cancer is well-documented, its involvement in viral infections is emerging." (PMID 40725077, 2025). "We further examined the relationship between ASS1 expression and STAT3 signaling in the context of viral infection." (PMID 42037409, 2026). "We demonstrate that ASS1 favors CHIKV replication and also plays important roles in several downstream cellular processes during virus infection." (PMID 42037409, 2026). "An increased expression of the Ass1 gene in piMφ suggests that arginine metabolism is active to allow bioavailability of this amino acid as a NOS2 substrate, since NO is essential to inhibit viral infection." (PMID 39296294, 2024). "Additionally, ASS1 expression affected STAT3 levels and its subcellular localization: ASS1 overexpression correlated with reduced nuclear STAT3 accumulation and increased viral replication, whereas ASS1 depletion promoted STAT3 nuclear translocation and restricted viral infection." (PMID 42037409, 2026). "However, much detailed mechanism was not investigated and in our study, along with ASS1, there was an increased in E3 ubiquitin ligase deltex 3L, PLSCR1 and serpin were increased, which might be one of the antiviral effects induced by the host cell during the early stage of viral infection." (PMID 32566414, 2020).
uveal melanoma (4 papers, 2022 to 2026). A melanoma derived from melanocytes of the uveal tract. "Uveal melanoma is a hard-to-treat arginine-dependent cancer secondary to argininosuccinate synthetase 1 (ASS1) loss with half of patients succumbing to liver-dominant metastases." (PMID 42322017, 2026). "Drug sensitivity of ASS1-deficient uveal melanoma cell lines was performed in 2D culture using proliferation and cytotoxicity assays, with analysis of cell death, cell cycle, DNA double-strand breaks, and interrogation of the molecular mechanism of action by RNA-seq." (PMID 42322017, 2026). "But high expression of ASS1 in BRCA, LGG, UCEC, and UVM (Uveal melanoma) patients was associated with poor OS (p=0.048, p=0.047, p=0.029, p=0.00064, respectively)." (PMID 38053661, 2023). "In contrast, although BAP1 loss was shown recently to induce ASS1 in malignant mesothelioma cell lines with an inverse correlation in clinical samples, the same relationship is not apparent in uveal melanoma." (PMID 35466524, 2022). "Moreover, the modulation of AKT by ASS1 is an active area for drug targeting in cutaneous and uveal melanoma." (PMID 35466524, 2022). "Additionally, we reported on widespread deficiency of ASS1 in a majority (74%) of 102 primary choroidal and ciliary body melanomas, despite the known 60–80% loss of BAP1 in uveal melanoma." (PMID 35466524, 2022).
Argininemia (3 papers, 2019 to 2025). Arginase deficiency is a rare autosomal recessive amino acid metabolism disorder characterized clinically by variable degrees of hyperammonemia, developing from about 3 years of age, and leading to progressive loss of developmental milestones and spasticity in the absence of treatment. "With the exception of Argininemia, Arg can be supplied to all patients with UCDs, while Cit should not be supplemented in Argininosuccinate Synthase 1 (ASS1) and Argininosuccinate Lyase (ASL) deficiencies." (PMID 40428324, 2025).